FLT3 (fms related receptor tyrosine kinase 3)
Diseases named in the same sentence as FLT3 in open-access papers (continued):
Sharing a sentence is not in itself a finding about the gene and the disease.
leukemia (continued). "Interestingly, GNF-7 preferentially inhibited cell proliferation of FLT3-ITD-dependent leukemia cells (MOLM-13 and MV4-11) in a dose-dependent manner, whereas it has no apparent cytotoxic effect on leukemia cells with FLT3-WT (THP-1 and U937) in low dose concentration." (PMID 38037057, 2023). "Therefore, the MUTZ-11 can be used to study the role of FLT3 in leukemia pathogenesis." (PMID 36982453, 2023). "Upon treatment with the kinase inhibitor crenolanib, which blocks the activity of the oncogenic transmembrane protein FMS-like tyrosine kinase 3 (FLT3) on leukemia cells, augmented surface expression of FLT3 could be observed specifically on FLT3-ITD+ AML cells." (PMID 36768665, 2023). "Moreover, we identified a different HOXA9-bound site distant from FLT3 in MLL-r leukemia cells." (PMID 38016946, 2023). "That some MYB target genes (such as KIT, CDK6 and FLT3) exhibit a degree of correlation with MYB levels amongst the patient datasets probably reflects a wide range of driver mutations and a very heterogeneous genetic landscape amongst the complex karyotype leukaemias." (PMID 37996430, 2023). "Though FLT3-ITD was reported to be a driver mutation in AML patients’ initiation of leukemia by FLT-3 through STAT pathway might not be the case for this patient." (PMID 35350997, 2022). "In line with the importance of CAMs in drug-resistance and the interplay of leukemia cells with the bone marrow niche, resistant cells showed significantly altered migration and adhesion properties, and both LPXN and PTK2B were upregulated in LSCs of FLT3-mutated patients." (PMID 36056084, 2022). "Recent data also demonstrate that HDAC8 upregulation is an important mechanism to resist FLT3 inhibitors and promote leukemia maintenance; thereafter, HDAC8 inhibition in combination with FLT3 inhibitor treatment could be a promising strategy to treat FLT3-ITD+ AML." (PMID 35656547, 2022). "Additional KMT2A/MLL-R+ patients whose leukemia cells do not have amplified FLT3 gene expression but an activating FLT3 mutation like FLT3-ITD may also benefit from the use of FLT3 inhibitors." (PMID 36627892, 2022). "However, midostaurin acts as an antagonist to some chemotherapeutic agents in leukemia cell lines without FLT3 mutations." (PMID 35810308, 2022). "One-third of AML patients have FLT3 mutations, and this mutation is associated with internal tandem duplication (ITD) in the JM domain of FLT3, promoting hyperactivation of tyrosine kinase signaling pathways coexisting with the expansion of the leukemia cell population." (PMID 36072760, 2022). "Finally, the FLT3 pathway is a robust druggable target in this aggressive form of leukemia." (PMID 35626079, 2022). "Therefore, new therapeutic strategies with molecular-level targets, particularly those that differ in their mode of action from classical kinase inhibition, might improve the clinical outcomes of patients with FLT3-ITD leukemia." (PMID 34035227, 2021). "Partial knockdown of the transcription factor STAT5 (STAT5A and STAT5B) in FLT3-ITD cells resulted in decreased ROS production, highlighting the oncogenic association between recurring somatic mutations and the necessity for leukaemia cells to maintain a state of oxidative dysfunction." (PMID 34679751, 2021). "MLL-PTD is not sufficient to cause leukemia alone; an additional FLT3-ITD could trigger leukemia in mice." (PMID 33836835, 2021).
leukemia (continued). "Gain-of-function mutations of FLT3 include internal tandem duplication (FLT3-ITD) and point mutations in the kinase domain (FLT3-TKD), each of which could lead to over-activated signals for proliferation and survival of leukemia cells." (PMID 32817792, 2020). "Using variant allele frequencies to infer the chronological sequence of these events in leukemia development, it was shown that mutations in DNMT3A likely develop first in hematopoietic stem cells (or other mutations causing CH), followed by NPM1c second in a CMP, and FLT3 mutations (or RAS) third." (PMID 32545659, 2020). "For DNA structural variants, FLT3 internal tandem duplication (ITD) positive cell line and patient samples showed a LOD of ≥0.001 in addition to previously unknown copy number losses in leukemia genes." (PMID 32131829, 2020). "Finally, plasma FST levels might be exploited as a surrogate biomarker of leukemia cell growth to evaluate treatment response to FLT3 inhibitors in FLT3/ITD AML." (PMID 32134197, 2020). "The recently discovered αvβ3 addiction of MLL-AF9 leukemia may also be FLT3-dependent." (PMID 30841639, 2019). "Our findings on the cooperation of Myb and C/EBPα in Flt3 gene regulation prompted us to investigate the global extent of this cooperation in leukaemia and to determine how manipulation of Myb expression might impact on the maintenance of C/EBPα-driven leukaemia." (PMID 30877232, 2019). "Therefore, we investigated why FLT3+ leukemia cells responded differently to FLT3L CAR-T cells." (PMID 29716633, 2018). "There are two types of FLT3 mutations, including approximately 20% of internal tandem duplications (FLT3/ITD) and 5~10% of point mutations in activating loop of tyrosine kinase domain (FLT3/TKD), constitutively activating cell proliferation and survival of leukemia blasts." (PMID 29301553, 2018). "In conclusion, FLT3 ligand-based CAR-T cells exhibited specific cytotoxicity against FLT3+ leukemia cell and had the ability to distinguish between FLT3 wild-type cells and FLT3-ITD mutant cells, which may be an ideal candidate that specifically target AML with FLT3 mutation." (PMID 29716633, 2018). "The importance or potential mechanism of high FLT3 expression in leukemias remains unknown." (PMID 28538663, 2017). "The largely overlapping transcriptional consequences of Syk and Meis1 led us to hypothesize that Meis1-transformed leukemias would be more addicted to Syk than to other signaling proteins such as Flt3, which has previously been shown to be dispensable for Meis1-driven leukemias." (PMID 28399410, 2017). "In addition, preclinical studies of FLT3-targeting chimeric antigen receptor T cell immunotherapy have demonstrated potent anti-leukemia activity in cell line and patient-derived xenograft models (Tasian, unpublished), further validating FLT3 as a robust therapeutic target in childhood AML." (PMID 29209600, 2017). "Nevertheless, mouse models indicate that the presence of a FLT3 mutation alone might not be sufficient to cause leukemia." (PMID 28538663, 2017). "Thus, although FLT3-ITD may be subclonal in some leukemias and is sometimes lost at relapse, our data ascertain the validity of FLT3-ITD as a TKI target to eliminate LIC." (PMID 29312564, 2017). "Azacitidine and cytarabine have the potential to induce differentiation of blasts, new targeted drugs like sorafenib and midostaurin may also be helpful in Fms-related tyrosine kinase 3 (FLT-3)-positive leukemia or panobinostat, an oral deacetylase inhibitor for MM." (PMID 28638379, 2017). "Even in patients with FLT3-mutated leukemia, a number of small molecule tyrosine kinase inhibitors with activity against FLT3 have been developed but, as of yet, none of the studied FLT3 inhibitors has not been used for routine clinical use in FLT3-mutated AML." (PMID 27906677, 2017). "In addition, only a subset of AMLs have a FLT3 mutation and targeted treatment options for leukemias without FLT3 mutation remain limited." (PMID 27834816, 2016).
leukemia (continued). "Furthermore, FLT3-ITD could cooperate strongly in leukemia induction with a variety of leukemia-initiating gene fusions such as AML1-ETO, MLL-AF9, or PML-RAR α." (PMID 25879624, 2015). "Based upon promising preclinical data in leukemia and clinical testing in solid tumor patients with platelet-derived growth factor receptor (PDGFR) mutations, a Phase 2 study of the third-generation FLT3/PDGFR inhibitor crenolanib in adults with AML is also in progress (NCT01522469)." (PMID 24672775, 2014). "Finally, combining FLT3 and CXCR4 inhibitors could overcome stromal protection of FLT3-activated leukemia cells and could be additive to any of the approaches above." (PMID 25295230, 2014). "Flt3 deficiency did not delay disease onset and had minimal impact on leukemia characteristics." (PMID 23977266, 2013). "In these investigations the therapeutic efficacy of PKC412 was restricted to MLL-rearranged leukemia cells carrying either FLT3 amplifications or FLT3 activating mutations; whereas no therapeutic benefit could be observed in cells in which FLT3 was unaltered." (PMID 23977266, 2013). "Although we showed that Flt3 was dispensable for the generation of leukemias induced by two distinct MLL fusion genes, both diseases were myeloid malignancies and we cannot rule out that FLT3 may be important in the pathogenesis of MLL-rearranged lymphoid malignancies." (PMID 23977266, 2013). "Moreover, human leukemia and lymphoma cell lines also express FLT3 protein." (PMID 24744665, 2012). "Our results differ from human leukemia in that we observed the FLT3 ITD mutation not infrequently in ALL (2/7 samples), whereas in humans, the FLT3 ITD mutation is only rarely seen in ALL (~1% of ALLs) and is much more common in AML (25% of adult cases; 15% of pediatric cases)." (PMID 21272320, 2011). "However, IGF1R is preferentially phosphorylated in wild type FLT3 leukemia cell lines." (PMID 21552520, 2011). "In contrast to the results from FLT3 -ITD MV-4-11 xenograft models, the administration of quizartinib at the dosage of 10 mg/kg showed minimal impact on the leukemia burden." (PMID 39955584, 2025). "MV4-11 cells present a FLT3-ITD mutation that renders a hyper-active and hyper-phosphorylated form of the FLT3 tyrosine kinase, which in turns phosphorylates STAT5B at Try699 to drive leukaemia progression." (PMID 40082888, 2025). "As expected, several previously reported genes with abnormal methylation in leukemias such as CPEB1, BLK, FLT3, ZCCHC7, EBF1, HDACs, IKZF1, RB1, CDK6, DOCK5, DPP10, MUC4, JAKs, KIT, KRAS, LINC01013, MAD1L1, NOTCH1, and STATs, among others, were also detected." (PMID 41226303, 2025). "AXL inhibition combined with FLT3 inhibition to decrease the ERK signal rebound and to exert greater anti‐leukemia effects than with either treatment alone." (PMID 39395205, 2025). "FMS-like tyrosine kinase 3 (FLT3) is notably overexpressed in AML, making the inhibition of this kinase a critical focus in leukemia therapy." (PMID 39860214, 2025). "Combination therapy in the FlT3-ITD AML xenograft model resulted in prolonged survival and reduced leukemia burden compared with single drugs." (PMID 40092706, 2025). "In this study, FLT3 and WT1 protein expression was used as markers of leukemia cell proliferation and was determined using Western blotting." (PMID 40361130, 2025). "We first determined the FLT3 and AKT protein levels in luekemia cell lines before mitoxantrone-liposomes treatment, then determined the FLT3 protein levels in the leukemia cell lines 12 h post-treatment with mitoxantrone-liposomes." (PMID 40092706, 2025). "Given the significant roles of FLT3 and WT1 in leukemia pathogenesis, ongoing research to identify natural bioactive compounds targeting these pathways is essential, as it offers the potential for effective therapies with minimal side effects." (PMID 40361130, 2025).
leukemia (continued). "To evaluate the impact of FASN on FLT3-ITD signaling, we generated stable FASN knockdowns via shRNA in two human leukemia cell lines, MOLM13 and MV411." (PMID 40565186, 2025). "Genes that have been reported as abnormally methylated in leukemia, including CPEB1, BLK, FLT3, PAX5, EBF1, HDACs, IKZF1, RB, etc., were also detected in this study." (PMID 41226303, 2025). "Prior research has indicated that IL1RAP can be targeted therapeutically to eliminate leukemia; however, the blocking activity of certain IL1RAP antibodies is ineffective in the context of FLT3-ITD." (PMID 40229904, 2025). "Both compounds induced concentration-dependent apoptosis in FLT3-ITD-positive MV4-11 cells, as shown by the sub-G1 phase in the cell cycle, with lesser effects in other leukemia cell lines." (PMID 39408703, 2024). "Some of these target genes include DNMT1 (DNA Methyltransferase 1), FLT3 (FMS-Like Tyrosine Kinase 3), and MLL (Mixed-Lineage Leukaemia)." (PMID 38902412, 2024). "Targeting either FLT3 or CD99 using FLT3-A192 or CD99-A192 led to AML cell death and reduced leukemia burden in AML mouse models." (PMID 39007347, 2024). "Preclinical trials have also shown that mice harboring both FLT3-ITD and NUP98 fusion genes exhibited more aggressive leukemia with a shorter latency period." (PMID 39273530, 2024). "Moreover, in a mouse model that carries the two most prevalent gene mutations in AML, Npm1c and Flt3-ITD, we observed an upregulation of SNORD118 expression as well as the expression of Rnu3b family members (mouse orthologs of human SNORD3A) upon leukemia induction by double mutations (DM)." (PMID 38942785, 2024). "A subpanel of leukemia was selectively inhibited by compound 5l, which has nanomolar IC50 values for FLT3 (IC50 = 36.21 ± 1.07 nM), and CDK2 (IC50 = 8.17 ± 0.32 nM)." (PMID 38794229, 2024). "The integrative analysis further suggested that the HOXA9/FLT3 axis promises the dominant downstream target of RBM5, as demonstrated by functional rescue assay and transcriptional regulation in leukemia cells." (PMID 38216972, 2024). "In fact, FLT3 is already used as a treatment biomarker in AML, and data from cell lines showed that FLT3L CAR-T cells specifically kill FLT3+ leukemia." (PMID 38339034, 2024). "They evaluated bulk leukemia cells from bone marrow or peripheral blood from 318 newly diagnosed or relapsed AML patients and found that 78% showed increased FLT3 protein expression." (PMID 39697225, 2024). "Targeting FLT3 or CD99 induces apoptosis in FLT3-ITD+ AML in vitro and reduces leukemia burden in vivo." (PMID 39007347, 2024). "It was reported that in FLT3-ITD AML, elevated ROS concentrations induced by oncogene signaling lead to compensatory enhancement of antioxidant capacity that protecting leukemia cells from oxidative damage, thereby bringing leukemia cells survival benefits." (PMID 37391442, 2023). "The failure of TKI targeting FLT3-ITD in patients with AML to prevent a recurrence, despite complete remission, suggests resistance and/or persistence of leukemia initiation cells in the hematopoietic niche." (PMID 36914737, 2023). "Western blot data showed that sitravatinib markedly reduced the levels of p-FLT3, p-STAT5, p-AKT and p-ERK in primary blasts, demonstrating that the anti-leukemia activity of sitravatinib was coupled with the suppression of FLT3 signaling pathways." (PMID 36691065, 2023). "In FLT3-internal tandem duplication (FLT3-ITD)-positive AML, a subtype of leukemia with notoriously dismal outcome, CB-839 also impaired GSH production, induced severe mitochondrial oxidative stress and cell apoptosis." (PMID 37032776, 2023).
leukemia (continued). "In fact, targeting BTK with ibrutinib shows anti-proliferative effects in AML by mediating suppression of FLT3 downstream signaling MAPK, AKT, and NF-κB; and combined inhibition of FLT3 and BTK reportedly has additive anti-leukemia effects." (PMID 36865133, 2023). "that proteasome inhibitor bortezomib is involved in degradation of FLT3-ITD oncoprotein via activation of autophagy, which leads to a cytotoxic apoptosis of leukemia cells in vitro." (PMID 37664023, 2023). "A previous study using a 42-plex human cytokine array to analyze the serum of NSG mice engrafted with Nalm6-GFP leukemia cells reported high levels of PDX-intrinsic PDGF-AA and FLT-3 L as well as lower levels of FGF-2, VEGF-A, and TNFα." (PMID 36860657, 2023). "GNF-7 inhibited the cell proliferation of Ba/F3 cells expressing FLT3-ITD and exhibited potently anti-leukemia activity on primary FLT3-ITD AML samples." (PMID 38037057, 2023). "Last, ZDHHC6‐mediated palmitoylation at Cys563 restrained cell surface localization of internal tandem duplication within FMS‐like tyrosine kinase 3 (FLT3‐ITD) protein, inhibited the activation of AKT and ERK, and leukemia cell growth." (PMID 36018061, 2023). "More remarkably, CB-839 and FLT3 inhibitors, including AC220 and gilteritinib, exerted synergistic pro-apoptotic effects and displayed more potent anti-leukemia effect." (PMID 37032776, 2023). "Incorporation of FLT3 inhibitors with chemotherapy or haematopoietic stem cell transplantation has significantly improved the prognosis of FLT3-ITD-positive AML in recent years, but high incidence of leukaemia relapse remains a problem to be solved." (PMID 35794565, 2022). "Considering the FGFR1 related leukemia are driven by both the full-length fusion kinase and the truncated tnFGFR1, we examined the long-term efficacy of the combination of FLT3 and FGFR1 inhibitors with our SCLL leukemia model." (PMID 35906694, 2022). "Although allogeneic stem cell transplantation is utilized in the treatment of patients with FLT3-ITD AML, these patients have a higher incidence of relapse and decreased leukemia-free survival when compared to those with non-FLT3-ITD AML." (PMID 35912243, 2022). "Accordingly, the combination of HDAC8i, 22d, and FLT3 TKI enhances the elimination of FLT3-ITD+ AML and reduces leukemia-initiating capacity in vivo." (PMID 36231123, 2022). "Other genes of interest are Flt3 and Atr, which were shown to be upregulated and to have a pathological role in CLL and other leukemias." (PMID 34417556, 2022). "We further show that de novo human AML also express tnFGFR1 which correlates with upregulation of FLT3 and KIT as in mouse leukemia cells." (PMID 35906694, 2022). "Orally disposable EC-70124 exerted a potent inhibitory effect on the growth of FLT3-ITDMUT AML cells, delaying disease progression and debulking the leukemia." (PMID 35326743, 2022). "We showed that CDDD11-8 induced apoptosis in the MV4-11 and MOLM-13 leukemia cell lines harboring the clinically relevant genetic aberrations of MLL fusion and FLT3-ITD." (PMID 35267421, 2022). "In summary, our findings point to a fusion protein-driven epigenetic mechanism of FLT3 activation in ALL and expand the armory of genomics-guided targeted therapy for this leukemia." (PMID 36104354, 2022). "PROM1, FLT3, CTGF, LGALS1, IGFBP7, ZNRF1, and RUNX2 were found highly expressed in the MLL-R pro-B ALL compared to the other subclassification of leukemia." (PMID 36276286, 2022). "Recipient mice engrafted with primary leukemia cell expressing wild type BCR-FGFR1 were treated with FGFR1 and FLT3 inhibitor alone or in combination." (PMID 35906694, 2022). "Overall, these results indicated that CDDD11-8 is most likely to induce apoptosis in the leukemia cell lines by modulating the cellular activity of CDK9 and FLT3." (PMID 35267421, 2022).